KLK6 (kallikrein related peptidase 6)
Diseases named in the same sentence as KLK6 in open-access papers (continued):
Sharing a sentence is not in itself a finding about the gene and the disease.
ovarian tumors (9 papers, 2002 to 2023). "Recent reports of an association between elevated KLK6 expression in primary ovarian tumors and poor prognosis indicate that KLK6-positive patients have increased risk of relapse and death." (PMID 27863404, 2016). "The collective expression of all KLK6 mRNA transcripts encoding the full-length protein was assessed in 16 ovarian tumour samples, eight with KLK6 overexpression (H1–H8) and eight with minimal KLK6 expression (L1–L8)." (PMID 17242704, 2007). "More abundant transcripts in LGSC-PT included the CA-125 binding partner mesothelin (MSLN) and the serine protease KLK6, which predicts the recurrence of borderline and low-grade ovarian tumors and is regulated by MAPK29." (PMID 38014221, 2023). "KLK6 and KLK7 mRNA and protein overexpression is directly associated with early-stage ovarian tumors and can be measured in patient tissue and serum samples." (PMID 25477184, 2014). "High KLK6 or KLK13 expression in primary ovarian tumours can significantly predict prognosis in terms of recurrence-free survival and overall survival." (PMID 19707197, 2009). "Transcripts corresponding to some of these proteins (e.g., KLK6, 7 and 9) are relatively abundant in ovarian tumors compared to most normal tissues." (PMID 18560578, 2008). "We used the median as the cutoff value to categorise the ovarian tumours as KLK6-positive or KLK6-negative." (PMID 17242704, 2007). "Conversely, the protein concentration of KLK6 in the 259 ovarian tumour cytosols ranged from 0.01 to 65 ng mg−1 of total protein, with a median of 2.83." (PMID 17242704, 2007). "KLK6 expression in ovarian tumour cytosols was found to be 57-fold higher than normal and 31-fold higher than benign and nonovarian metastatic tumours (P<0.0001)." (PMID 17242704, 2007). "We first conducted a validation study to confirm the prognostic significance of KLK6 in a large group of ovarian tumour tissues using a new immunoassay of higher sensitivity and specificity than previously reported." (PMID 17242704, 2007). "In addition, it has been shown that RNA‐interference‐suppressed KLK6 impedes tumor cell growth and the formation of metastases, while ectopic KLK6 expression increases ovarian tumor proliferation." (PMID 37609678, 2023). "Conversely, the KLK6 expression in ovarian tumour cytosols was significantly upregulated." (PMID 17242704, 2007).
colon adenocarcinoma (8 papers, 2009 to 2025). "KLK6, KLK7, KLK8, and KLK10 were recently reported as potential diagnostic biomarkers for colon adenocarcinoma." (PMID 36293321, 2022). "Recently, The Cancer Genome Atlas (TCGA) RNA-Sequencing data analysis of kallikrein gene expression across 15 different cancers highlighted KLK6, KLK7, KLK8, and KLK10 as good candidates for colon adenocarcinoma potential diagnostic biomarkers." (PMID 35883559, 2022). "Recent analysis of kallikrein gene family across 15 different cancers highlighted KLK6, KLK7, KLK8, and KLK10 as the excellent diagnostic biomarkers candidates for colon adenocarcinoma." (PMID 34065672, 2021). "The tumors in TCGA patients with KLK6-high and KLK6-low groups were identified as colon adenocarcinomas." (PMID 34065672, 2021). "Here we evaluated the cellular functions of KLK6 protease in Caco-2 colon adenocarcinoma cell line after introduction of the enzymatically active or inactive form of the enzyme." (PMID 31692974, 2019). "Thus, Caco-2 colon adenocarcinoma cell line acquired the invasive and metastatic properties upon overexpression of active KLK6 protease." (PMID 31692974, 2019). "Interestingly, analysis of gene expression from TCGA showed that KLK6 may be a suitable prognostic predictor for colon adenocarcinoma." (PMID 35883559, 2022). "KLK6, KLK7, KLK8 and KLK10 are considered as excellent biomarker candidates in diagnosing colon adenocarcinoma." (PMID 40156045, 2025). "Only KLK6, COL11A1, and WNT2 has been found to be suitable prognostic predictors for colon adenocarcinoma." (PMID 35883559, 2022). "Immunohistochemistry (IHC) analysis demonstrated ectopic expression of KLK6 in human colon adenocarcinomas but not in normal epithelia." (PMID 35883559, 2022). "Patient data support this phenotype as IHC analysis showed ectopic expression of KLK6 in human colon adenocarcinomas but not in normal epithelia." (PMID 35883559, 2022).
pancreatic cancer (8 papers, 2004 to 2022). "The role of KLK6 in pancreatic cancer might be further explored in vivo by using for example an orthotopic xenograft approach, whereby tumour spheroids established from KLK6-expressing and KLK6-deficient PDAC cells are positioned adjacent to the pancreas." (PMID 34439122, 2021). "We then validated KLK6 mRNA and protein expression in patient-derived tissues and pancreatic cancer cells." (PMID 34439122, 2021). "This is in line with an earlier in silico analysis demonstrating that the KLK6 mRNA is expressed at a high density in pancreatic cancer, whereas the KLK6 protein was undetectable in the pancreas using a highly sensitive immunofluorometric assay." (PMID 34439122, 2021). "We aimed to investigate the expression of KLKs in pancreatic cancer and to inhibit the function of KLK6 in pancreatic cancer cells." (PMID 34439122, 2021). "KLK10 and KLK6 are co-expressed in pancreatic cancer tissues, positively correlated with R1-resection status and poor prognosis and are independent risk factors." (PMID 31612115, 2019). "KLK10 and KLK6 are among the most highly and specifically overexpressed genes in pancreatic cancer compared with normal and benign pancreas tissues." (PMID 18854834, 2008). "Since KLK8is typically co-expressed with KLK6 in multiple disease contexts,including in pancreatic cancer,16,29−31 initial probe development focused on an ABP selective toward KLK6over KLK8, a challenging objective in view of their common trypsin-likespecificity for Lys/Arg at P1." (PMID 36413626, 2022). "The high expression of KLK6 might thereby play an important role in various pathologic processes of pancreatic cancer." (PMID 18854834, 2008). "KLK6, KLK7, KLK8, KLK10 and KLK11 were coexpressed and upregulated in tissues from pancreatic cancer patients compared to normal pancreas." (PMID 34439122, 2021). "Our findings confirm the KLK6-specific effects as APPI-4M reduced the KLK6 secretion of pancreatic cancer cells, while KLK10 secretion was not affected." (PMID 34439122, 2021). "We previously reported that some biomarkers, such as human kallikreins 6 and 10 (KLK6 and KLK10) are consistently elevated in about 2–5% of pancreatic cancer sera, at 100% specificity, leading us to query if such biomarkers have any role to play in clinical practice." (PMID 29872704, 2017). "Although high expression in pancreatic carcinoma indicates that KLK6 and 10 could be promising tumour markers, we could not assess the use of KLK6 and KLK10 as serum biomarkers in PDAC." (PMID 18854834, 2008).
pancreatic ductal adenocarcinoma (7 papers, 2008 to 2025). An infiltrating adenocarcinoma that arises from the epithelial cells of the pancreas. "Previous studies suggested an upregulation of KLK10 and KLK6 in pancreatic ductal adenocarcinoma (PDAC)." (PMID 18854834, 2008). "Recent research has identified KLK6 as a promising prognostic biomarker in various cancers, while the co-expression of KLK6 and KLK10 has been suggested as a potential indicator of survival outcomes in pancreatic ductal adenocarcinoma." (PMID 40428321, 2025).
head and neck squamous cell carcinoma (6 papers, 2015 to 2026). A squamous cell carcinoma that arises from any of the following anatomic sites: lip and oral cavity, nasal cavity, paranasal sinuses, pharynx, larynx, and salivary glands. "So far, the expression of KLK6 in head and neck squamous cell carcinoma (HNSCC) and its association with pathological features or the clinical outcome has not been addressed in larger patient cohorts." (PMID 25990935, 2015). "However, in head and neck squamous cell carcinoma, higher levels of KLK6 were associated with favorable patient survival." (PMID 41509368, 2025). "However, in head and neck squamous cell carcinoma (HNSCC), higher levels of KLK6 were associated with favorable patient survival." (PMID 41597241, 2026). "KLK6 expression was decreased in head-neck squamous cell carcinoma, in contrast to earlier findings." (PMID 29707153, 2018). "Additionally, it has been shown that not only the loss of KLK6 but also the loss of SOX2 expression induces cell motility via vimentin up-regulation and is an unfavorable risk factor for survival of head and neck squamous cell carcinoma." (PMID 28671620, 2017). "Five KLKs were commonly downregulated in head-neck squamous cell carcinoma and breast invasive carcinoma: KLK3 (3-fold and 4-fold), KLK6 (2-fold and 6-fold), KLK7 (2-fold and 10-fold), KLK11 (5-fold and 6-fold) and KLK13 (8-fold and 3-fold)." (PMID 29707153, 2018). "However, the expression of KLK6 in carcinomas derived from mucosal epithelia, including head and neck squamous cell carcinoma (HNSCC), and its mode of action has not been addressed so far." (PMID 25990935, 2015).
multiple sclerosis (6 papers, 2011 to 2024). A progressive autoimmune disorder affecting the central nervous system resulting in demyelination. "KLK6 is a secreted serine protease abundantly expressed by oligodendrocytes, long implicated in CNS disease, especially multiple sclerosis." (PMID 38880880, 2024). "Altered expression and activity of KLK6 have been linked to brain physiology and the development of multiple sclerosis." (PMID 32655372, 2020). "Further, KLK6 was found elevated in the serum of multiple sclerosis patients with highest levels being associated with secondary progressive disease." (PMID 23216878, 2012). "Interestingly, at the date, the possible role or differential regulation/function of KLK8 and/or KLK6 in multiple sclerosis or other neural diseases associated with viral infections remains to be elucidated." (PMID 32655372, 2020). "In contrast, elevated levels of KLK6 have been observed in multiple sclerosis patients and its role in the disease pathology has been related to an immuno-inflammatory pathway, particularly by activating PAR receptors, key triggers of inflammatory processes." (PMID 27186164, 2016). "Human kallikrein-related peptidase 6 (KLK6) has been implicated in various types of cancer and in neurodegenerative and demyelinating diseases including multiple sclerosis." (PMID 23216878, 2012). "Further, anti-KLK6 antibodies attenuated disease manifestations in the mouse model of multiple sclerosis." (PMID 23216878, 2012). "KLK6 has been considered an early biomarker in the context of traumatic brain injury in rats, whereas it has been put forward as a therapeutic target in multiple sclerosis and for AD patient care." (PMID 35458486, 2022). "Thus, high levels of KLK6 have been found in actively demyelinating multiple sclerosis and spinal cord injury." (PMID 32655372, 2020). "High levels of KLK6 may favor the progression of multiple sclerosis through an excessive cleavage of myelin basic protein, the most widely studied myelin protein in this disease." (PMID 32655372, 2020). "Additional studies functionally link Klk6 to the onset and progression of multiple sclerosis since elevation in systemic KLK6 during the disease may lead the immune system towards a pro-inflammatory response that may exacerbate the disease by favoring neuroinflammation." (PMID 32655372, 2020). "Notably, KLK6 is also elevated in the serum of multiple sclerosis (MS) patients however its potential roles in immune function are unknown." (PMID 21464892, 2011).
cervical carcinoma (5 papers, 2014 to 2022). A carcinoma arising from either the exocervical squamous epithelium or the endocervical glandular epithelium. "KLK6 was proposed as a biomarker for human papilloma virus-positive cervical cancer, axonal injury in HIV infection, and for patient prognosis in glioblastoma follow-up." (PMID 35458486, 2022). "KLK6 expression was monitored on transcript and protein levels in three well-established HNSCC cell lines (FaDu, Cal27 and SCC25) as well as one cervix carcinoma cell line (HeLa)." (PMID 25990935, 2015). "KLK6 expression was detected in head and neck tumor cell lines (FaDu, Cal27 and SCC25), but not in HeLa cervix carcinoma cells." (PMID 25990935, 2015).
synucleinopathies (5 papers, 2014 to 2022). "Based on the ability of KLK6 to cleave α-synuclein and its decreased expression in patients, KLK6 was linked to PD and other synucleinopathies." (PMID 27845893, 2017). "Because KLK6 levels are reduced in patients with synucleinopathies including PD, restoring KLK6 levels may represent a possible therapeutic intervention for these neurodegenerative diseases." (PMID 35349763, 2022). "CSF levels of KLK6 are reduced in patients with synucleinopathy including PD." (PMID 27845893, 2017). "Taken together, these two studies indicated that KLK6 could represent a novel therapeutic protein for PD and other synucleinopathies." (PMID 27845893, 2017). "KLK6 level is also reduced in CSF in patients with synucleinopathy." (PMID 25476568, 2014).
breast invasive carcinoma (4 papers, 2018 to 2026). "A separate report found increased levels of KLK6 in serum from patients with invasive breast cancer, compared to healthy controls, suggesting a role in disease progression and poor prognosis." (PMID 41597241, 2026). "A separate report found that increased levels of KLK6 in serum from patients with invasive breast cancer, compared to healthy controls, suggesting a role in disease progression and poor prognosis." (PMID 41509368, 2025).
breast tumors (4 papers, 2002 to 2019). "In contrast, re-expression of KLK6 at physiological concentrations dramatically inhibits the growth of primary breast tumors and causes marked reduction of vimentin." (PMID 21072173, 2010). "In particular, KLK6 was originally discovered as being highly upregulated in a primary breast tumor but inactivated in the corresponding lung metastases." (PMID 30980596, 2019).
glioblastoma (4 papers, 2015 to 2022). The most malignant astrocytic tumor (WHO grade IV). "The KLK6/PAR1 axis was linked to glioblastoma multiforme and injuries of the central nervous system." (PMID 34439122, 2021). "Expression of KLK6 RNA is also linked to poor patient survival in a group of intracranial malignancies, including glioblastomas, meningiomas, oligodendrogliomas, ependymomas and other rare malignancies and brain metastases." (PMID 26231762, 2015).
psoriasis (4 papers, 2014 to 2022). An autoimmune condition characterized by red, well-delineated plaques with silvery scales that are usually on the extensor surfaces and scalp. "Moreover, multiple studies have suggested that KLK6 is associated with various inflammatory diseases including psoriasis, atopic dermatitis, and inflammatory joint disease." (PMID 36552865, 2022). "However, KLK6 overexpression causes psoriasis and inflammatory arthritis via signaling through PAR1." (PMID 36552865, 2022). "High levels of the KLK6 protein have been detected in individuals with various skin diseases such as psoriasis and atopic dermatitis, and rheumatoid arthritis; KLK6 promotes psoriasis dermatitis and inflammatory joint disease via PAR1 signaling." (PMID 36552865, 2022). "Our results are consistent with reports regarding the increased KLK6 expression in several proliferative skin diseases such as psoriasis and atopic dermatitis, as well as in human premalignant skin lesions and squamous cell carcinomas." (PMID 27283773, 2016). "Experiments with mice showed an increase in KLK6, KLK7, and KLK8 mRNA levels when Psoriasis-like lesions were induced." (PMID 35356049, 2021). "Namely, RHCG, TCN1, KLK6, and LCN2 were chosen for psoriasis and CCL17, NCF4, BATF3, and CLEC4G as ACD-specific genes." (PMID 25058585, 2014). "However, the same experience conducted in KLK8 knockout mice did not result in KLK6 and KLK7 mRNA upregulation, suggesting a determinant role of KLK8 in proteolytic cascade in Psoriasis." (PMID 35356049, 2021).
renal carcinoma (4 papers, 2011 to 2021). A carcinoma arising from the epithelium of the renal parenchyma or the renal pelvis. "KLK5 and KLK6 are decreased in all three types of the renal carcinomas." (PMID 29707153, 2018). "KLK expression is cell- and tissue-dependent, and although KLK6 and KLK7 have been suggested to promote tumor cell invasion, loss of KLK5 has been observed in prostate, lung, breast, testicular, and renal cancer tissues versus their normal counterparts, similar to our PDAC data presented herein." (PMID 22203845, 2011).
renal cell carcinoma (4 papers, 2013 to 2025). "In renal cell carcinoma (RCC), KLK6 expression varies by subtype and tends to be elevated in more aggressive tumors, correlating with advanced staging and poorer survival, making it a potential biomarker for RCC subtyping." (PMID 40428321, 2025). "In an earlier study using immunohistochemical analysis, KLK6 and KLK7 have been shown to have lower expression in high grade, in contrast to low grade renal cell carcinoma." (PMID 29707153, 2018). "In terms of renal cell carcinoma (RCC), clinical experimental studies have proven that some KLKs, such as KLK1, KLK3, KLK6, KLK7, and KLK15, are differentially expressed in different subtypes of RCC, and KLK6 has predictive value in RCC." (PMID 39116105, 2024).
serous ovarian cancer (4 papers, 2009 to 2021). "High KLK6 mRNA expression was associated with the presence of serous ovarian cancer and late stage disease." (PMID 19707197, 2009). "In supplementary analysis, when we compared serous to non-serous ovarian cancers (mucinous, endometrioid, clear cell, and unknown), high KLK6 expression was associated with serous carcinomas (P=0.001; data not shown)." (PMID 19707197, 2009). "The set of upregulated keratins, i.e., 6A, 6B, 15, 16, 19, 80, in the KLK6-high CRC tumors was different from the one, identified in KLK6-overexpressing serous ovarian cancer." (PMID 34065672, 2021). "A recent study using western blots of serum depleted of high abundance proteins suggests that serum KLK6 levels are elevated in early stages of serous ovarian cancer." (PMID 29051715, 2017). "Therefore, it is not too surprising that we observed indication for coordinate expression of some KLKs such as KLK6/KLK8 (Spearman correlation of mRNA levels: rs = 0.636;), KLK10/KLK11 (rs = 0.647;), or KLK5/KLK7 (rs = 0.568; unpublished results) in advanced high-grade serous ovarian cancer." (PMID 30811511, 2019).
skin tumor (4 papers, 2021 to 2022). "A recent study showed that KLK6 deficiency mediates the resistance to skin tumor development and that this resistance may be associated with reduced 7,12-dimethylbenz[a]anthracene/12-O-tetradecanoylphorbol 13-acetate (DMBA/TPA)-induced inflammation." (PMID 36552865, 2022). "Enhanced KLK6 expression in skin cancer is associated with malignant progression." (PMID 36552865, 2022). "KLK6−/− mice induced with carcinogenesis developed fewer tumors compared to wild-type animals, suggesting that KLK6 has a role in skin tumor development and progression." (PMID 35356049, 2021). "Recent research has shown that KLK6−/− mice are highly resistant to skin tumor growth and development and that this resistance may be associated with reduced TPA-induced inflammation." (PMID 36552865, 2022). "MRNA levels of KLK6, LCN2 and FOSL1 were found to be significantly overexpressed in UV-induced skin tumours in K14-HPV8-CER mice compared to FVB/N wild-type skin, collected 24d after irradiation." (PMID 35406439, 2022).
bladder urothelial cancer (3 papers, 2018 to 2025). "Additionally, KLK6 overexpression in ovarian, breast, colorectal, and bladder urothelial cancer tissues has been associated with a poor prognosis." (PMID 40428321, 2025). "In our study, we attempt to explore the biological functions of KLK6 in bladder urothelial carcinoma (BLCA)." (PMID 36193495, 2022).